RN7SL543P (RNA, 7SL, cytoplasmic 543, pseudogene)
Gene: Miscellaneous RNA gene on chromosome 16 (67,019,519 to 67,019,817, forward strand). Ensembl gene ENSG00000265918.
Homologues: Orthologues: chimpanzee Metazoa_SRP (99% identical), chimpanzee Metazoa_SRP (98% identical), chimpanzee Metazoa_SRP (94% identical), macaque Metazoa_SRP (94% identical). Paralogues in human: RN7SL1 (86% identical), RN7SL2 (86% identical), RN7SL492P (84% identical), RN7SL3 (83% identical), RN7SL127P (83% identical), RN7SL296P (82% identical), RN7SL444P (82% identical), RN7SL709P (82% identical), RN7SL45P (82% identical), RN7SL478P (82% identical), RN7SL50P (82% identical), RN7SL300P (82% identical), and 707 more.